CTSB (cathepsin B)
Diseases named in the same sentence as CTSB in open-access papers (continued):
Sharing a sentence is not in itself a finding about the gene and the disease.
testicular germ cell tumor (1 paper, 2022). A germ cell tumor arising from the testis. "In the urinary and male reproductive tracts, CTSB was expressed more highly in kidney renal clear-cell carcinoma (KIRC), kidney renal papillary cell carcinoma (KIRP), and testicular germ cell tumors (TGCT) compared with the normal tissues." (PMID 35155389, 2022).
tongue SCC (1 paper, 2018). "We have previously reported the expression of cathepsin B and cathepsin D by CSC subpopulations within oral tongue SCC and IDHWGB, suggesting the presence of bypass loops for the RAS." (PMID 30177970, 2018).
Ureteral obstruction (1 paper, 2020). Obstruction of the flow of urine through the ureter. "Interestingly, using a model of unilateral ureteral obstruction, the authors found that CTSB or CTSL deficiency in mice exacerbates kidney fibrosis, whereas CTSS or CTSK deficiency protects it." (PMID 33379277, 2020).
urothelial bladder cancer (1 paper, 2016). "CTSD and CTSB activities in the sera of patients with urothelial bladder cancer were identified to be directly proportional to disease severity, and were significantly higher compared to those of the control group." (PMID 26995190, 2016).
vasculitis (1 paper, 2021). "The HMGB-1/RAGE signaling pathway in endothelial cells also induces cathepsin B activation, subsequently inducing canonical pyroptosis via NLRP3 inflammasomes in KD vasculitis." (PMID 34079539, 2021). "Moreover, Nucleotide-binding oligomerization domain-like receptor family, pyrin domain-containing 3 (NLRP3)-dependent endothelial cell pyroptosis via HMGB-1/RAGE/cathepsin B signaling may contribute to coronary artery endothelial cell (CAEC) damage in KD vasculitis." (PMID 34079539, 2021).
tumor (531 papers, 1998 to 2026). "This probe leverages Angiopep-2-mediated targeting of LRP1 receptors to facilitate efficient BBB crossing, followed by a cascaded activation process triggered specifically by the tumor-associated enzymes cathepsin B (Cat B) and monoamine oxidase (MAO)." (PMID 41665406, 2026). "Biomarkers such as Ki67, HSP60, Survivin, PD-L1, E-cadherin, Stathmin, and Cathepsin B have shown significant associations with tumor progression, metastasis, and poor prognosis, supported by the results from the studies analyzed." (PMID 40818120, 2026). "In cancer, the myokine, cathepsin B, is associated with initiation, tumour growth/proliferation, angiogenesis, invasion and metastasis, although its overexpression can induce apoptosis of cancer cells." (PMID 41300368, 2025). "Conversely, cathepsins such as Cathepsin B and K are implicated in promoting tumor invasion and metastasis, emphasizing their critical role in the tumor microenvironment." (PMID 39312365, 2024). "The summarized key findings emphasize cathepsin B's association with tumour grade and stage, shedding light on its multifaceted roles in OSCC pathogenesis." (PMID 38500921, 2024). "For instance, increased glucose uptake in M2-like tumor-associated macrophages fuels HBP for lysosomal OGT-mediated Cathepsin B O-GlcNAcylation to elevate its mature form and then promotes tumor metastasis and chemoresistance." (PMID 38575607, 2024). "Elevated levels of CTSB alone or in combination with other proteolytic enzyme pathways have also been associated with tumor progression." (PMID 37576397, 2023). "Our stability data indicates that the enzymatic digestion of Val-Cit-PABC-R848 leads to a rapid release of the R848 payload, which can be mediated in vivo by Cathepsin B and other tumor-associated proteases for which the Val-Cit linker is a substrate." (PMID 38125888, 2023). "Changes in the activity of CTSB and the endogenous inhibitor stefin A are associated with tumor progression and prognosis and can be used as prognostic factors in cancer patients." (PMID 37576397, 2023). "Cathepsin B, the most abundant and ubiquitously expressed exopeptidase of the papain family, is associated with tumour progression in numerous cancer types, including colorectal, breast, lung, pancreatic, and gastric cancer." (PMID 37958596, 2023). "Recent data proved that CtsB is implicated in tumor extracellular matrix remodeling, cell invasion, and metastasis: a misbalance between cathepsins and their natural inhibitors is often considered a sign of disease progression." (PMID 35563761, 2022). "CTSB can degrade the extracellular matrix, such as collagen, matrix fiber and proteoglycans, to cause dissolution of the tumor matrix and the basement membrane, promoting invasion and metastasis." (PMID 35872750, 2022). "When cathepsin B was present on the surface of tumor cells, it acted like “scissors”, chopping peptide fragments, releasing metabolic precursors, and causing tumor cells to generate unnatural glycans containing azide groups." (PMID 36072925, 2022). "Many studies have exploited this phenomenon in delivering nano-based chemotherapeutics, such as using HPMA enzyme-linked systems that are specifically cleaved by tumor-specific enzymes, such as cathepsin B." (PMID 35163777, 2022). "For example, the expression of CTSB (an exopeptidase, acting as an exo- or endopeptidase) and its enzymatic activity are associated with high tumor aggressiveness and grade in GBM." (PMID 36552871, 2022). "Though the role of CTSB in solid tumors has been completely certified, its up-regulation is nearly associated with tumor's progression." (PMID 35992541, 2022). "Overall, these data show that an increase in the CtsB/STFA ratio (higher CtsB expression accompanied by StfA impoverishment) can cause a more aggressive tumor phenotype." (PMID 35563761, 2022).
tumor (continued). "As a corollary to the CTSB knockdown-associated reduction in tumor growth, we assessed the impact of CTSB overexpression on RCC 786-O xenografts." (PMID 30796200, 2019). "Having demonstrated the fundamental role of CTSB in tumor growth, we next attempted to elucidate the underlying molecular mechanisms." (PMID 30796200, 2019). "Cathepsin B-producing macrophages are associated with increased local tumor recurrence during perineural invasion (PNI)." (PMID 30818851, 2019). "Enzymatic activity of CTSL+B and CTSB exhibited a strong positive association with tumor stage and lymph node involvement in GBC (p < 0.050)." (PMID 31824841, 2019). "Well studied PTs, including OpaxioTM, PGA conjugates and HPMA copolymer conjugates, have taken advantage of the activity of the cathepsin protease family and especially the tumor-associated overexpression of cathepsin B." (PMID 29360800, 2018). "Expression of cathepsin B has been associated with tumor invasiveness and metastasis in multiple types of cancer." (PMID 29455656, 2018). "Tumors from ParvOryx-treated patients that were NS1- and/or viral RNA-positive displayed markers of local activation of tumor-associated microglia/macrophages, such as CTSB." (PMID 28967558, 2017). "Protein encoded by CTSB regulates negatively Wnt/β-catenin signaling pathway related with tumor development." (PMID 28402931, 2017). "High levels of expression of cathepsin B have been observed in epithelial tumours and glioblastoma, and are implicated in tumour development and progression via initiation, proliferation, angiogenesis, invasion, inflammation, apoptosis and metastasis." (PMID 28146084, 2017). "Cleavage of the commonly used dipeptide linker depends on tumor-associated lysosomal cathepsin B and undergoes rapid hydrolysis, leading to release of the parent drug to kill the tumor." (PMID 28841157, 2017). "Our study demonstrated that CTSB expression was significantly associated with positive lymph node metastasis and higher tumor grade." (PMID 27031837, 2016). "Typically, CtsB-overexpressing HT-29 tumour cell and CtsB-deficient NIH/3T3 cells were chosen as models to incubate with enzyme-responsive CRUN (50 μg ml−1) at 37 °C for 4 h." (PMID 26786559, 2016). "Cathepsin B is a lysosomal cysteine proteinase, which has been implicated in a variety of diseases, such as inflammation and tumor metastasis." (PMID 25351637, 2015). "In human diseases, experimental and clinical evidence have linked cathepsin B with tumor invasion and metastasis." (PMID 26691339, 2015). "Pericellular acidosis scattered around tumor cells, leads to the “redistribution” of the cell surface and an increased secretion of active cathepsin B, a lysosomal cysteine protease involved in degrading processes associated with tumor invasion." (PMID 23992304, 2014). "To validate the efficiency of targeting to the tumor microenvironment in vivo and to investigate the potency of the CtsB-targeted system for diagnostic applications, we applied magnetic resonance imaging (MRI)." (PMID 24975267, 2014). "Given that CTSB is proteolytic enzyme expressed at high levels in vasculature during vBM degradation associated with tumor angiogenesis, CTSB promotes the degradation of vBM together with other proteolytic enzyme such as MMP9 in SSc." (PMID 22384200, 2012). "Regarding angiogenesis, murine CTSB in vasculature is remarkably up-regulated during the degradation of vascular basement membrane associated with tumor angiogenesis." (PMID 22384200, 2012). "Tumor derived cathepsin B is quite often associated with tumor cell invasion and increased metastasis." (PMID 21853032, 2011). "This expression pattern is consistent with the metastatic property of 4T1 tumors, since lipocalin is negatively associated to angiogenesis and metastasis, while cathepsin B is positively correlated to tumor growth and metastasis." (PMID 21853032, 2011).
tumor (continued). "In tumor cells, cathepsin B redistributes into exocytic vesicles at the cell periphery leading to its secretion and association with the tumor cell surface by binding to the light chain of the annexin II heterotetramer." (PMID 22093547, 2011). "Altogether, these observations establish live imaging of cathepsin B activity with sensitive near infrared probes as a highly specific method for detection of biological activity linked with progressive tumor growth." (PMID 18698347, 2008). "In this study we have shown that cathepsin B activity is an inherent component of cancer-associated inflammation in tumor infiltrating myeloid cells." (PMID 18698347, 2008). "In malignant tumours and premalignant lesions, increased cathepsin B mRNA expression is associated with elevated cathepsin B protein levels and activity and correlates with tumour invasion." (PMID 18475293, 2008). "Cathepsin L, although less well studied than cathepsin B, has been linked to tumor invasion and metastasis." (PMID 17488522, 2007). "This novel ET‐CORM‐antibody conjugate releases carbon monoxide upon cleavage by the tumor‐associated protease cathepsin B. The construct enables selective intracellular CO delivery to HER2‐overexpressing and CatB‐expressing cells, presenting a new strategy for targeted, CO‐based cancer therapies." (PMID 41199686, 2026). "Moreover, increased cathepsin B expression has been observed in several malignancies, including breast, colorectal, and oral squamous cell cancers, where it is associated with tumor invasion, autophagy, angiogenesis, and metastasis." (PMID 40135201, 2025). "Additionally, enhanced Cathepsin B production by tumor and associated cells as well as reducing tumor environment due to release of thiols by dead tumor cells can be reasoned for cleavage of peptide and di-sulphide bonds of drug conjugates respectively." (PMID 38216921, 2024). "However, a 2016 study in the Journal of Biological Chemistry, focusing on colorectal tumour progression, demonstrated that elevations in cathepsin B expression were associated with tumour malignancy." (PMID 38500921, 2024). "Moreover, cathepsin B+ tumor‐associated macrophages overactivates CD8+ T cells, leading to an enrichment of granzyme K+ senescent CD8+ T cells in MIA." (PMID 37991139, 2023). "Cathepsin B acts as a cysteine cathepsin often associated with tumor progression." (PMID 35814405, 2022). "Consistent with the findings described here, many studies have demonstrated that a high expression level of CtsB and StfA was associated with cancer, higher tumor grade, and poor prognosis in patients; however, the CtsB and StfA relation in RCC was not checked." (PMID 35563761, 2022). "Previous studies in tumor tissues suggested that oxidative stress could cause elevation of secreted cathepsin B and MMPs, which contributed to the digestion of extracellular matrix during tumor metastasis." (PMID 35239671, 2022). "Macrophages from mice deficient for cathepsin B and S are impaired in their ability to prevent cell death in tumor cells upon taxol treatment, compared to the wild‐type macrophages, indicating that cathepsins B and S are key proteases necessary for this process." (PMID 35349763, 2022). "Moreover, FRRG peptide is a well-known substrate of cathepsin B, which is associated with tumor invasion and metastasis as a promising cancer biomarker overexpressed in malignant tumors compared with normal tissues in clinical studies." (PMID 35056979, 2021). "Often, cancer cells and tumor-associated Mɸ overexpress cathepsins, such as CTSB and CTSZ." (PMID 32385587, 2021). "The quenched fluorescence and singlet oxygen production ability is recovered due to the degradation of the poly-L-lysine by tumor-associated protease cathepsin B. A poly-D-lysine backbone (D-SR16) that is uncleavable by proteases was synthesized for comparison." (PMID 34805129, 2021).
tumor (continued). "Moreover, the surgical specimen also exhibited spindle tumor cells that frequently included neutrophils, around which intense staining for lysosomal-associated membrane protein 1 and cathepsin B was observed." (PMID 34452644, 2021). "Cathepsin B belongs to a family of lysosomal cysteine proteases comprising disulfide-linked heavy and light chains, which can directly or indirectly degrade the extracellular matrix in tumor tissues." (PMID 32154176, 2020). "Contrary to Ctsb deficiency, which counteracts tumor growth by multiple mechanisms, other means to interfere with the mitotic, chromatin-associated CTSB activity may favor the survival of cells with genomic instability and thereby promote tumorigenesis." (PMID 31932607, 2020). "Furthermore, mutation of cathepsin B or S impairs tumor formation and angiogenesis, whereas knock-out of cathepsin B or L decreases cell proliferation and tumor growth." (PMID 30818851, 2019). "Having established the diagnostic and prognostic significance of CTSL and CTSB overexpression in the tumor tissues of GBC, it was of interest to investigate if the levels of these cathepsins in serum could accurately discern GBC patients from controls." (PMID 31824841, 2019). "Furthermore, the activity of CTSL+B and CTSB showed a significant association with tumor stage and lymph node involvement in GBC patients." (PMID 31824841, 2019). "Moreover, cathepsin B was reported to be implicated in tumor progression, and cathepsin B-sensitive G4-GLFG-H-R has potential applications in gene delivery and cancer therapy." (PMID 30970901, 2017). "The overproduction of cathepsin B by tumour cells and tumour-associated cells may at least be partly involved in cleavage of ADCs present in a tumour mass either in extracellular spaces or after target antigen binding." (PMID 29065110, 2017). "The tumour-promoting activities of SMV-associated cathepsin B may occur specifically in acidic compartments of the tumour milieu, as it becomes activated at low pH." (PMID 24009895, 2013). "H-1PV induced immunomodulatory effects within the tumor microenvironment, including increased infiltration of cytotoxic T-cells and activation of tumor-associated microglia/macrophages, as evidenced by the upregulation of cathepsin B, iNOS, and accumulation in CD40L-positive tumor regions." (PMID 40867316, 2025). "Additionally, cathepsin B (Cath B) is correlated with therapy resistance, and overexpression of this protease is associated with invasive phenotypes of many cancers; moreover, this protein has been demonstrated to have a tumor-protective role." (PMID 36552000, 2022). "Furthermore, tumour associated macrophages and stromal fibroblasts highly express cathepsin B." (PMID 29065110, 2017). "Specifically, we proposed that incorporating a cathepsin B (CatB) cleavage site would enable tumor‐specific intracellular CO release, while introducing a bioorthogonal handle would allow tumor targeting through conjugation to a suitable antibody." (PMID 41199686, 2026). "Extracellular cathepsin B is a driver of tumor progression and metastasis, and its potential as a diagnostic and prognostic marker is increasingly recognized." (PMID 41988367, 2026). "Cathepsin B/D is a key member of the protease family that promotes tumor invasion, migration, and angiogenesis by degrading and remodeling the ECM." (PMID 40861820, 2025). "To overcome this limitation, we designed H62, a tumor-selective prodrug conjugating the DHODH inhibitor EA6 with the STING agonist MSA-2 via a cathepsin B-cleavable linker." (PMID 41239499, 2025). "Once in the tumor microenvironment, where cathepsin B is overexpressed, the polymer backbone undergoes enzymatic degradation into small fragments." (PMID 40305357, 2025). "Cathepsin B is a cysteine protease involved in tumor progression and represents a potential therapeutic target in various human cancers and is also known to play a key role in invasion and migration in tumor cells." (PMID 40566630, 2025).